ABCC9 (ATP binding cassette subfamily C member 9)
Diseases named in the same sentence as ABCC9 in open-access papers (continued):
Sharing a sentence is not in itself a finding about the gene and the disease.
Intellectual disability (7 papers, 2019 to 2026). "This new cohort underscores that AIMS is characterized by the combination of periventricular leukomalacia, developmental delay and intellectual disability, and muscle weakness and fatigability - and is driven by biallelic loss-of-function variants in ABCC9." (PMID 42290677, 2026). "Autosomal recessive loss-of-function variants in ABCC9 cause ABCC9-related Intellectual disability and Myopathy Syndrome (AIMS)." (PMID 42290677, 2026). "Loss-of-function mutation of ABCC9, the gene encoding the SUR2 subunit of ATP sensitive-potassium (KATP) channels, was recently associated with autosomal recessive ABCC9-related intellectual disability and myopathy syndrome (AIMS)." (PMID 38217872, 2024). "Loss‐of‐function (LoF) mutation of ABCC9 (SUR2) results in ABCC9‐related intellectual disability and myopathy syndrome (AIMS), characterized by fatigability, spasticity, and cramping." (PMID 37154692, 2023). "Here, the authors report recessive ABCC9 mutations in individuals with mild intellectual disability, myopathy and cardiac systolic dysfunction which is associated with loss of KATP channel function." (PMID 31575858, 2019). "ABCC9 loss-of-function mutations cause ABCC9-related Intellectual disability Myopathy Syndrome (AIMS), another complex condition that includes intellectual disability with white matter hyperintensities detected by MRI, even in teenagers." (PMID 34526147, 2021). "Notably, in subjects with developmental delay, intellectual disability and fatigability the presence of PVL-like changes associated with progressive microcephaly, temporal white matter involvement and scattered calcifications should raise the suspicion of an ABCC9-related disorder." (PMID 38217872, 2024).
atrial fibrillation (6 papers, 2015 to 2025). A disorder characterized by an electrocardiographic finding of a supraventricular arrhythmia characterized by the replacement of consistent P waves by rapid oscillations or fibrillatory waves that vary in size, shape and timing and are accompanied by an irregular ventricular response. "In humans, loss of function mutations in ABCC9, the gene responsible for SUR2, are associated with the development of dilated cardiomyopathy, atrial fibrillation and ABCC8-related Intellectual disability Myopathy Syndrome (AIMS)." (PMID 37109544, 2023). "ABCC9 variants impair the ATP-sensitive potassium channel function, and through this mechanism, it is believed to facilitate arrhythmogenesis in DCM and atrial fibrillation (AF)." (PMID 36008935, 2022).
breast carcinoma (5 papers, 2020 to 2025). "The ABCC9 gene is associated with poor prognosis in women with breast cancer, and the minoxidil treatment is associated with an elevated number of breast cancer cases that we reported here." (PMID 37180726, 2023). "ABCC9 is significantly downregulated in breast cancer and ABCC9tetra is particularly prone to mutation." (PMID 35071399, 2021). "Mutations of the ABCC9 gene were reported in large granular lymphocyte leukemia, endometrial, gastric, and breast cancers." (PMID 37180726, 2023). "Regarding mutation frequency, the highest mutation rates in breast cancer tissues were observed in ABCC2 and ABCC9." (PMID 40641097, 2025). "The ABCC9 and KCNJ8 genes’ upregulation was associated with a reduced probability of survival in lung squamous cell carcinoma in males and the ABCC9 gene also in bladder and breast cancers in white female patients." (PMID 37180726, 2023). "Another study on the methylation pattern of breast cancer revealed that ABCC9 is a potential grade III biomarker of breast cancer in white individuals." (PMID 35071399, 2021). "Similarly, the ABCC9 and KCNJ8 genes’ upregulation was associated with a reduced probability of survival in lung squamous cell carcinoma in males, and the ABCC9 gene also in bladder and breast cancers in white female patients." (PMID 37180726, 2023). "Deep deletions were significantly more prevalent in prostate cancer than in breast cancer, with frequent occurrences in ABCG2, ABCG1, ABCC4, ABCA2, ABCC2, ABCC7/CFTR, and ABCC9." (PMID 40641097, 2025). "In contrast, breast cancer exhibited relatively lower deep deletion rates, restricted to ABCG2, ABCC4, ABCA2, ABCC2, and ABCC9." (PMID 40641097, 2025). "Deep deletions were significantly more prevalent in prostate cancer tissues compared to breast cancer tissues, where they were relatively rare and limited to ABCG2, ABCC4, ABCA2, ABCC2, and ABCC9." (PMID 40641097, 2025). "We tested the role of the ABCC8/Sur1, ABCC9/Sur2A/B, KCNJ11/Kir6.2, and KCNJ8/Kir6.1 genes experimentally in a minoxidil-induced renal tumor in male rats and in the female canine breast cancer, a spontaneous animal model of disease, and in the pharmacovigilance and omics databases." (PMID 37180726, 2023). "The Kir6.2-Sur2A/B-channel opener minoxidil showed 23 case reports of breast cancer and one case of ovarian cancer in line with omics data reporting, respectively, and the negative and positive prognostic roles of the ABCC9 gene in these cancers." (PMID 37180726, 2023). "The role of the ATP-binding cassette (ABC) transporters in tumorigenesis of White breast cancer patients is further supported by the enrichment of the “brown” module in basal transcription factors, including the ATP-binding cassette subfamily members ABCA9, ABCC9, ABCG2, ABCB1, ABCA6, and ABCA8." (PMID 32873298, 2020).
intellectual disability myopathy syndrome (5 papers, 2019 to 2024). "ABCC9‐related intellectual disability and myopathy syndrome (AIMS) arises from loss‐of‐function (LoF) mutations in the ABCC9 gene, which encodes the SUR2 subunit of ATP‐sensitive potassium (KATP) channels." (PMID 37154692, 2023). "Biallelic loss-of-function mutations in ABCC9 are linked to intellectual disability myopathy syndrome (AIMS), with neurological symptoms such as mild-to-moderate cognitive impairments, white matter abnormalities, and anxiety." (PMID 37294764, 2023).
diabetes (4 papers, 2018 to 2025). "Mutations in ABCC9 impair cardiac stress adaptation, leading to myocardial damage and are associated with diabetes and obesity." (PMID 41458991, 2025). "SNPs in ATP-sensitive potassium channel (KATP) subunits KCNJ8 (Kir6.1) and ABCC9 (SUR2) might influence the presence of diabetes, and they seem to be involved in ischemic heart disease pathogenesis." (PMID 30344267, 2018).
gastric cancer (3 papers, 2021 to 2024). A primary or metastatic malignant neoplasm involving the stomach. "The enrichment analysis of gastric cancer found that ABCC9 was involved in ATPase activity, transmembrane transport, and ABC transporters." (PMID 35071399, 2021). "The results indicated upregulation of ABCC9 in gastric cancer." (PMID 38396807, 2024).
prostate carcinoma (3 papers, 2022 to 2025). A carcinoma that arises from epithelial cells of the prostate gland. "In contrast, prostate cancer tissues exhibited frequent deep deletions in ABCG2, ABCG1, ABCC4, ABCA2, ABCC2, ABCC7/CFTR, and ABCC9." (PMID 40641097, 2025). "For example, eight ABC transporter genes (e.g., ABCA8, ABCC6, and ABCC9) were significantly downregulated in prostate cancer tissues compared with noncancerous tissues." (PMID 35280774, 2022).
arterial hypertension (2 papers, 2022 to 2024). "Here, we report another case of a LOF ABCC9 genetic variant associated with idiopathic ventricular tachycardia and arterial hypertension." (PMID 35495129, 2022). "Here, we reported a patient with a LOF variant in the ABCC9 gene (Leu1524LysfsTer5, rs869025349) associated with a complex clinical phenotype, including arterial hypertension and stress-induced ventricular arrhythmia." (PMID 35495129, 2022). "Importantly, hypertension was also reported in the patient’s father carrying the same ABCC9 variant." (PMID 35495129, 2022). "To conclude, we presented the second case of the heterozygous ABCC9 LOF variant in a patient with arrhythmogenic cardiac phenotype, arterial hypertension, and no signs of structural heart diseases." (PMID 35495129, 2022). "Minoxidil had the most negative correlation coefficient (−0.3101) and is a hypertension medication that targets KCNJ8, KCNJ11, and ABCC9." (PMID 39713369, 2024).
cervical cancer (2 papers, 2023 to 2024). A primary or metastatic malignant neoplasm involving the cervix. "The findings highlighted upregulation of ABCC9 in cervical cancer." (PMID 38396807, 2024).
Cognitive impairment (2 papers, 2023 to 2024). Abnormal cognition is characterized by deficits in thinking, reasoning, or remembering. "Our studies further confirm the association of LoF variants in ABCC9 with a neurodevelopmental disorder featuring cognitive impairment, childhood hypotonia, seizures, contractures, spasticity and myopathic features, alongside white matter abnormalities often resembling periventricular leukomalacia." (PMID 38217872, 2024).
coronary artery vasospasm (2 papers, 2020 to 2025). "ABCC9–/– mice exhibit elevated resting blood pressure, ST segment elevation, and coronary vasospasm." (PMID 41458991, 2025). "ABCC9 knock-out mice showed elevated blood pressure and coronary artery vasospasm." (PMID 32251481, 2020).
delusional disorder (2 papers, 2018 to 2019). A disorder characterized by the presence of one or more nonbizarre delusions that persist for at least 1 month; the delusion(s) are not due to schizophrenia or a mood disorder, and do not impair psychosocial functioning apart from the ramifications of the delusion(s). "One somatic mutation in the patient with delusional disorder showed a missense variant in ABCC9 with an allele fraction of 7.32%." (PMID 29654278, 2018). "A previous meta-analysis of GWAS research revealed that ABCC9 is associated with sleep duration, indicating that somatic mutations of this gene may be associated with delusional disorders." (PMID 30087451, 2019). "Among the seven TAS-validated HC sites, four were missense variants, including one in ABCC9 (ATP-binding cassette, sub-family C, member 9) with an AAF of 7.32% in the patient with delusional disorder." (PMID 29654278, 2018). "In addition, we identified a missense somatic mutation in ABCC9 in one twin with a delusional disorder, which was not present in the healthy cotwin." (PMID 30087451, 2019).
epithelial ovarian cancer (2 papers, 2020 to 2023). "Minoxidil showed a P.R.R. for cancer of 1.65 within the KATP channel openers with only one case of ovarian cancer in line with the proposed role of the ABCC9/Sur2 as a positive prognostic factor in this type of cancer." (PMID 37180726, 2023). "This investigation revealed that both Kir6.2 (KCNJ11) and SUR2 (ABCC9) proteins can be expressed in ovarian cancer." (PMID 32457608, 2020). "Interestingly, a differential expression analyses revealed that the ABCC9 (SUR2) gene is significantly downregulated in human ovarian cancer tissues independently of their histological characterization and in uterine cancer." (PMID 32457608, 2020).
familial atrial fibrillation (2 papers, 2020 to 2025). An autosomal dominant heart condition that causes disruptions in the heart's normal rhythm. "Mutations in ABCC9 are associated with dilated cardiomyopathy type 10 and familial atrial fibrillation (type 12)." (PMID 40943070, 2025).
pericardial effusion (2 papers, 2021 to 2022). Fluid collection within the pericardial sac, usually due to inflammation. "Regular monitoring of cardiac function is recommended because ABCC9 gene deletion is known to cause pericardial effusion and cardiomegaly." (PMID 35052368, 2021).
pituitary adenoma (2 papers, 2018 to 2023). "Minoxidil treatment is a pharmacological animal model of C.S. This disorder is associated with G.O.F. mutations of the ABCC9 and KCNJ8 genes, and some cases of familial pituitary adenoma were found in C.S. families." (PMID 37180726, 2023). "Familial pituitary adenomas have a heterogeneous genetic background, and further studies are needed to see if there is indeed a link with ABCC9." (PMID 29327300, 2018).
angina pectoris (1 paper, 2022). The symptom of paroxysmal pain consequent to MYOCARDIAL ISCHEMIA usually of distinctive character, location and radiation. "The Abcc9 protein product is activated by nicorandil, approved to treat angina pectoris." (PMID 35454087, 2022).
arteriolosclerosis (1 paper, 2021). The thickening of the wall of the small arteries and arterioles. "Thus, ABCC9 dysregulation may partly underlie the observation (i.e., may help to explain the phenomenon) that arteriolosclerosis is more severe in brains with LATE/HS than non-LATE/HS brains." (PMID 34526147, 2021).
cardiac hypertrophy (1 paper, 2020). "Cardiac hypertrophy is also present in genome-edited “Cantú mice,” in which human disease-associated mutations were introduced into either the endogenous ABCC9 or KCNJ8 genes, despite no apparent alteration of KATP channel properties in the ventricular myocytes of KCNJ8-mutant (Kir6.1wt/VM) mice." (PMID 32865539, 2020). "Consistent with this hypothesis, we recently demonstrated that downregulation of KATP function in smooth muscle, using transgenic, tissue-specific, dominant-negative Kir6.1 subunits, reverses cardiac hypertrophy in ABCC9-mutant (SUR2wt/AV) mice." (PMID 32865539, 2020).
cryptorchidism (1 paper, 2023). The failure of one or both testes of a male fetus to descend from the abdomen into the scrotum during the late part of pregnancy. "As previously reported, cryptorchidism was common in male dogs with SCDY/DCM, with 10 of 15 males homozygous for ABCC9 p.R1186Q having unilateral or bilateral cryptorchidism." (PMID 37239348, 2023).
cystic fibrosis (1 paper, 2019). Autosomal recessive disorder caused by pathogenic variants in the CFTR gene (cystic fibrosis transmembrane conductance regulator), which encodes a chloride and bicarbonate channel expressed in epithelial cells, and follow the diagnosis criteria. "Moreover, CBZ has been shown to correct the trafficking defect of ΔF508 CFTR (ABCC9), the most prevalent mutation underlying cystic fibrosis." (PMID 31343405, 2019).
familial restrictive cardiomyopathy (1 paper, 2019). An instance of restrictive cardiomyopathy that is caused by an inherited modification of the individual's genome. "We discuss the case of a 43-year-old patient diagnosed with familial restrictive cardiomyopathy with positive genetic tests for mutations of MYH7 gene and ABCC9 gene, who was first hospitalized in 2011 for palpitations." (PMID 32309617, 2019). "Here, we describe the case of a 43-year-old patient diagnosed with familial restrictive cardiomyopathy, with mutations in MYH7 and ABCC9 genes." (PMID 32309617, 2019).
glioma (1 paper, 2024). A benign or malignant brain and spinal cord tumor that arises from glial cells (astrocytes, oligodendrocytes, ependymal cells). "The AQP4 aggregation state similarly and significantly caused an upregulation of the KCNJ11, ABCC8, and ABCC9 genes in U87 glioma cells." (PMID 39200356, 2024). "Conducting an extensive search using PubMed on glioma/brain-cancer-related articles of ABCC8, ABCC9, KCNJ11, KCNJ8, AQP4, and KCNMA1 genes has yielded interesting results." (PMID 39200356, 2024). "In the present work, we showed that the AQP4 aggregation into the pathogenic AQP4-tetramer and AQP4-OAPs differently affected the expression profile of KCNMA1, KCNJ11, ABCC8, and ABCC9 genes but not of the KCNJ8 gene in the U87 glioma cell, evaluated by the RTPCR gene expression." (PMID 39200356, 2024).
hearing loss (1 paper, 2022). "Human loss-of-function mutations in the ABCC9 gene are associated with mild sensorineural hearing loss." (PMID 35454087, 2022).
Hypercholesterolemia (1 paper, 2025). An increased concentration of cholesterol in the blood. "The majority (76%) of these randomly selected DEGs in 3xTg-AD mice did not appear as DEGs following CBD treatment, noting absence of some select markers for neurological aging (e.g., Abcc9 and Postn), hypercholesterolemia (e.g., Acat3), and inflammation (e.g., Alox8)." (PMID 40979532, 2025).
insomnia (1 paper, 2016). A sleep disorder characterized by difficulty in falling asleep and/or remaining asleep. "Although not directly related to insomnia per se, a recent GWAS of sleep duration found that ABCC9, important for KATP channels, was relevant, again pointing to an important role for ion channel function." (PMID 27999387, 2016).
long QT syndromes (1 paper, 2021). "PVs and LPVs in the ABCC9, AKAP9, ANK2, and SCN10A have been implicated in conduction defects and arrhythmias, particularly the long QT syndromes and conduction defects." (PMID 34790974, 2021).
lung adenocarcinoma (1 paper, 2021). A carcinoma that arises from the lung and is characterized by the presence of malignant glandular epithelial cells. "Targeting PLK1 with shRNA or non-functional mutants downregulated ABCB1, ABCC9, and ABCG2 in paclitaxel-resistant lung adenocarcinoma (LUADTXR), similar to the downregulation effects from treatment with PLK1 inhibitors." (PMID 34503223, 2021).
lung carcinoma (1 paper, 2021). "Thus, paclitaxel-resistant lung cancers are more sensitive to gefitinib and readily undergo apoptotic cell death compared with non-resistant lung cancer, through downregulation of ABCB1, ABCC9, ABCG2, PLK1, and EGFR." (PMID 34503223, 2021).
lymphedema (1 paper, 2023). Excess fluid collection in tissues, causing swelling. "In this issue of Function, Davis and colleagues use mouse models of CS to investigate the underlying mechanism of primary lymphedema with GoF mutations in the KATP channel genes Kcnj8 and Abcc9." (PMID 37342412, 2023).
melanoma (1 paper, 2022). A malignant, usually aggressive tumor composed of atypical, neoplastic melanocytes. "A query of human tumor transcriptomic data for 471 melanoma patients from The Cancer Genome Atlas (TCGA) dataset revealed a positive correlation of IGF1 and ABCC9, ABCG1, ABCB1, and ABCC4 with GHR expression, and ABCC1 with both GHR and IGF1R expression, supporting our observations." (PMID 35865483, 2022).
Nystagmus (1 paper, 2024). Rhythmic, involuntary oscillations of one or both eyes related to abnormality in fixation, conjugate gaze, or vestibular mechanisms. "The new cohort showed conserved features, including nystagmus, seizures, tendon abnormalities and lumbar lordosis, but also present with additional distinctive pathologies, expanding the ABCC9-related phenotype spectrum." (PMID 38217872, 2024).
pancreatic cancer (1 paper, 2023). "non-cancerous tissues in almost all the common cancers, ABCC9 is also prevalently downregulated except for the kidney renal clear cell carcinoma and pancreatic cancer which showed an upregulation vs." (PMID 37180726, 2023).
pancreatic ductal adenocarcinoma (1 paper, 2023). An infiltrating adenocarcinoma that arises from the epithelial cells of the pancreas. "Also, the ABCC9 gene expression was correlated with a low risk of progression in pancreatic ductal adenocarcinoma in white females (H.R. values = < 1)." (PMID 37180726, 2023).
primary lymphedema (1 paper, 2023). A congenital condition that results in swelling in the arms or legs, and can occur during adolescence or adulthood. "Indeed, a recent report describes a patient originally diagnosed with primary lymphedema who was subsequently found to have a GoF mutation in ABCC9 and was rediagnosed with CS." (PMID 37214333, 2023).
short QT syndrome (1 paper, 2023). A genetic disease of the electrical system of the heart that consists of a constellation of signs and symptoms, consisting of a short QT interval on an EKG (< 300 ms) that does not significantly change with heart rate, tall and peaked T waves, and a structurally normal heart. "KCNJ8 and ABCC9: Mutations in both KCNJ8 (Kir6.1) and ABCC9 (SUR2A) genes can result in a gain-of-function effect in the IK-ATP channel, leading to abnormal action potential characteristics associated with BrS or short QT syndrome phenotypes." (PMID 37443825, 2023).